STAT3 (signal transducer and activator of transcription 3)
Diseases named in the same sentence as STAT3 in open-access papers (continued):
Sharing a sentence is not in itself a finding about the gene and the disease.
cancer (continued). "The products of many of these oncogenes—such as STAT3, KRAS, or MYC—are CCT substrates; hence, each patient whose cancer overexpresses CCT could be treated without the need of molecular subtyping the downstream substrates." (PMID 29299146, 2017). "Our findings further reveal miR-500a-3p promotes the cancer stem cell characteristics via targeting multiple negative regulators of JAK/STAT3 signaling pathway, including SOCS2, SOCS4 and PTPN11, leading to constitutive activation of STAT3 signaling." (PMID 28750679, 2017). "Based on these studies, the authors also proposed that in EBV+ cancers characterized by type II latency (i.e., lacking EBNA2), STAT3 may drive LMP1 expression." (PMID 27458446, 2016). "As the NPM-ALK/STAT3 signaling pathway is not the key contributing factor to the differential expression of MYC, we turned to the Wnt/β-catenin pathway, which has been well documented to upregulate MYC in a variety of human cancers." (PMID 27821172, 2016). "Interestingly, JAK2/STAT3 signaling has been shown to promote fibrosis, angiogenesis, and inflammation in the setting of portal hypertension, independent of the presence of malignancy suggesting that regional inflammation also plays a role in abdominal pain, whether or not cancer is present." (PMID 26538823, 2015). "However, the potential anti-cancer effects of garcinol in HCC cancer model and in the context of STAT3/JAK2 signaling cascade as well as STAT3 acetylation have not been investigated yet." (PMID 24655440, 2014). "Most slides from cancer-free tissue lacked expression of CCND1, CD44, CDH1, EGFR, ERBB2, KIT, keratins, NOTCH1, PAK1, PTGS2, SNAI1, and VIM but showed staining of MUC1, HIF1A, NKX2-1, SFTPC, and STAT3, which were also found in AdCa." (PMID 23028920, 2012). "Thus, STAT3-decoy ODN inhibits STAT3 only in cells where STAT3 is activated, such as cancer cells, resulting in cell death without harming healthy cells." (PMID 21486470, 2011). "Majority of HPV- precancer, cancer and normal tissues lacked expression of STAT3 and pSTAT3 while only a small number of HPV16+ precancers (n = 6/16; 37%) and cancers (n = 12/58; 21%) had no or low STAT3 expression." (PMID 20977777, 2010). "However, in these cancer cells, LIF induces cell survival through signaling pathways that would not involve Stat3 activation." (PMID 17925034, 2007). "In addition, the downregulation of IL6-JAK-STAT3 signaling in the high-risk samples was inconsistent with the enrichment of M2-type macrophages, which indicates that non-classical activation of STAT3, such as through the EGFR or inflammasome pathway, is the dominant driver of cancer." (PMID 41601652, 2026). "In this sense, OPB-51602, the small-molecule inhibitor of STAT3 phosphorylation was evaluated in phase I (NCT01423903) multiple dose escalation clinical trial to determine safety and tolerability in subjects with advanced cancers for whom there is no standard treatment available." (PMID 40940764, 2025). "To further investigate the connection between STAT1, STAT3 and said cytokines in drug resistance, we have treated cells (EP and LP) with cytokine-neutralized (IL-6, IL-10 and IL-1β) MDSC supernatant (in presence or absence of these cytokines), keeping untreated cancer cells as a control." (PMID 38304256, 2023). "We also decided to investigate the anticancer effect of the STAT3 decoy strategy in TNBC because a novel molecular targeting approach is urgently needed, and the decoy strategy as a single treatment has not yet been explored for this type of cancer, to the best of our knowledge." (PMID 35847174, 2022). "However, it is not clear whether the IL‐6/STAT3 pathway is regulated by the canonical Wnt/β‐catenin pathway in the malignant progression of CRC and other cancers." (PMID 34997691, 2022).
cancer (continued). "We therefore speculated that, similar to other pathway-targeted cancer drugs, cell lines in which the nintedanib-driven blockade of the FGFR/SRC/STAT3 axis fails to fully suppress STAT3 activity could activate the JAK/STAT3 axis as a compensatory mechanism, which might be responsive to silibinin." (PMID 34439322, 2021). "Moreover, STAT3 activation was independent of gp130/JAK activity or HER2/EGFR heterodimer formation and administration of PD173074 led to suppression of STAT3 activation and inhibition of cancer cell proliferation." (PMID 34830951, 2021). "However, the total STAT3 protein expression decrease observed in the highest concentration (equal to IC50) of ATL and GER has not been reported previously when highly proliferative cancer cell lines were used." (PMID 32521813, 2020). "Since SOCS2 elevation is often considered to be the consequence of STAT3 activation and acts a negative feedback mechanism, SOCS2 might highly express in those STAT hyper-activated cases, of which might originally be greater malignant tumor." (PMID 31801484, 2019). "Once STAT3 is activated by phosphorylation, this TF interacts with the mitochondrial import protein GRIM-19 and is translocated from the cytosol to the mitochondria in both noncancer (heart and liver cells, lymphocytes) and cancer (HRAS-transformed human bladder T24 carcinoma) cells." (PMID 31600993, 2019). "However, the anti-cancer effects of icariin in MM cells had not been extensively investigated, although icaritin a hydrolitic product of icariin has been reported to modulate IL-6/JAK2/STAT3 signaling cascade in MM." (PMID 29899697, 2018).
infection (469 papers, 2006 to 2026). The state of being infected such as from the introduction of a foreign agent such as serum, vaccine, antigenic substance or organism. "Loss‐of‐function (LOF) variants, typically in the DNA‐binding or SH2 domain, reduce STAT3 phosphorylation and transcriptional activity, causing autosomal‐dominant Hyper‐IgE syndrome with eczema, recurrent infections, high IgE and impaired Th17 development." (PMID 41527523, 2026). "Regardless, loss-of-function infection experiments indicate that the loss of SOCS/SHP-2 binding cannot explain the SarA GBS domain’s increased induction of STAT3 phosphorylation compared to the gp130 GBS domain." (PMID 40188438, 2025). "We illustrated that the activation of STAT3 occurs during late infection and implicated the TRP75 effector in STAT3 phosphorylation." (PMID 41115066, 2025). "Although we determined that STAT3 contributes to the anti-apoptotic profile established during infection, our findings indicate that STAT3 likely possesses other functions associated with its role in promoting infection." (PMID 41115066, 2025). "This rapid transition from infection to structural damage, especially in patients with STAT3 mutations, highlights the importance of early and aggressive intervention." (PMID 40462219, 2025). "Thermal dysregulation in SWS has been linked to impaired JAK/STAT3 pathway signalling, which also affects immune function, thereby increasing susceptibility to infection." (PMID 41211063, 2025). "Our findings reveal that RSV utilizes a virus-specific and STAT3-dependent mechanism of apoptotic cell death to cause severe infection in infant bronchial epithelium." (PMID 39484716, 2024). "In our infection model of myeloid STAT3 deficiency, autocrine IL-10 is most likely the major component of the defective inflammation loop leading to the hyperinflammatory macrophage phenotype." (PMID 37982695, 2024). "We observed that the bacteria had rapidly translocated to the lungs at 12 h after infection in both STAT3-deficient and WT mice." (PMID 37982695, 2024). "Lungs from STAT3-deficient mice displayed higher inflammatory scores than WT lungs at 36 h of infection." (PMID 37982695, 2024). "Inhibition of STAT3 signaling has been implicated in some cell lines during infection with several viruses including Marburg virus, human metapneumovirus, Ebola virus and Kaposi’s sarcoma-associated herpesvirus." (PMID 37378295, 2023). "Direct activation of the signal transducer and activator of transcription 3 (STAT3) by the parasite enhances the anti-inflammatory function of TGFβ causing lifelong infection by establishing an anti-apoptotic environment." (PMID 35464478, 2022). "To this end, we explored how loss of Il-22, Il-18, or epithelial Stat3 in mice affects stem cells at the steady state or during AIEC infection." (PMID 35169117, 2022). "S. aureus can also cause infections in immunocompetent individuals; the predisposition of STAT3-HIES patients towards this pathogen, however, offers further insights into the immune defense against S. aureus." (PMID 35655107, 2022). "Infection of TCTs seemed to cause fewer alterations, but stronger effects on phosphorylation; CL monoinfection greatly increased STAT-3 activation, mainly in M0 and M(IFN-γ) groups." (PMID 36389843, 2022). "Pathogen infection causes an acute phase response and is accompanied by activation of the STAT3 signalling pathway." (PMID 36059492, 2022). "Analysis of the mixed population of PEC by qPCR detected increased transcription of STAT-3 and in the later stage of infection also STAT-6, which are associated with anti-inflammatory processes." (PMID 33461599, 2021). "We also found that in neutrophils, STAT3 pSer727 levels associated with development of secondary infections." (PMID 34016897, 2021).
infection (continued). "Infection of the STAT3-deficient neutrophils in presence of eosinophils, thus accelerated neutrophil cell death and had the potential to negatively impact pathogen burden and tissue pathology in the HIES subjects." (PMID 33271763, 2020). "We found that in contrast to the hybrid Th1/Tfh cells found in WT mice upon infection, T cells from T cell-specific STAT3-deficient mice (Stat3fl/flCD4Cre, STAT3 TKO) preferentially differentiated into Th1 memory cells (IFN-γ+IL-21−T-bethi)." (PMID 32634740, 2020). "Our data showed the activation of GSDMD, along with the phosphorylation of STAT3 and NF-κB, caused by P. aeruginosa, but the activation was abolished by the oprC deficiency strain infection." (PMID 32849593, 2020). "In this study, A. baumannii induced STAT3 phosphorylation in WT BMDMs starting 2 h after infection, a process which was impaired in IL-10-deficient macrophages." (PMID 32153580, 2020). "Remarkably, A. baumannii strongly induced STAT3 phosphorylation in WT macrophages after 2 h of infection but was reduced in IL-10-deficient cells." (PMID 32153580, 2020). "In this respect, LEPR mutation (Q223R) or polymorphism (rs1137101), which is a homozygous allelic mutation that results in impaired STAT3 signaling is likely to increase the susceptibility for dissemination of infection." (PMID 32824322, 2020). "Most notably pathways associated with the Aryl Hydrocarbon Receptor (AhR), an important emerging modulator of inflammatory signaling, IL-17 and STAT3 associated signaling were more highly repressed or less activated during APEC O2-GFP infection." (PMID 31998322, 2019). "We highlight that STAT3 expression in APCs inhibits TH17 associated responses resulting in an increased susceptibility to infection with M. tuberculosis." (PMID 29338039, 2018). "MuV is yet another example in which the cytopathic effects of infection are associated with the induction of apoptosis, partly via V protein-mediated STAT3 degradation." (PMID 29543893, 2018). "In summary, we here showed using SOCS3- and STAT3-deficient mice that STAT3 in myeloid cells is detrimental for the control of infection with M. tuberculosis." (PMID 29338039, 2018). "STAT3 is a key regulator in inflammation and tissue regeneration triggered by almost every pathogenic infection." (PMID 29543893, 2018). "Stat3fl/fllysm cre mice, deficient in STAT3 in myeloid cells, showed lower bacterial levels in organs and reduced extension of lung granulomas after infection with M. tuberculosis." (PMID 29338039, 2018). "Hepcidin upregulation in the context of inflammation/infection is typically linked to signaling via the IL-6/STAT3 pathway." (PMID 26394303, 2015). "Evaluating possible co-association of STAT3 with TAK1 with molecular sensors of infection is a focus of our ongoing studies." (PMID 25419841, 2014). "I.v. treatment of Cyld−/− mice with STAT3 siRNA 24 h before infection resulted in 80% reduction of total STAT3 in the liver, which caused reduced fibrin deposition in Cyld−/− mice." (PMID 23825949, 2013). "This multidirectional, fundamental role of Th17 cells, including cells with specificities against candidal antigens explains the pattern of infection susceptibility characteristic of STAT3 mutated HIES patients." (PMID 22085750, 2011). "Genes linked to STAT3 during infection were associated with GO terms such as regulation of cell proliferation (CCND1, JUNB), negative regulation of apoptosis (MCL-1, NFKB1), cytokine-mediated signaling pathway (IL10RA, SOCS1), and immune system process (CRK, IRF9)." (PMID 41115066, 2025). "This suggests that RSV actively modulates the immune system by suppressing STAT3 activation, which could contribute to the virus’s ability to persist and cause recurrent infections." (PMID 40407543, 2025). "EBV mobilizes host STAT3, a transcription activator implicated in the induction of proliferative and anti-apoptotic genes, to relax the ongoing checkpoint response activated in B cells by infection." (PMID 41009395, 2025).
infection (continued). "Given that HSP90 is associated with STAT3 on the cellular membrane during temperature-switch treatment or GCRV infection, we examined whether VP7 interacted with HSP90 and STAT3 in CIK cells." (PMID 37099596, 2023). "While infection with the translocation-deficient ΔvirD4 mutant or the bacteria lacking bepD did not trigger STAT3 activation, we found higher levels of phosphorylated STAT3 at 3 hpi if B. taylorii wild-type was cultured at 28°C." (PMID 35910598, 2022). "If blockade of p38 MAPK and STAT3 signalling increases iNOS levels causing reduced intracellular bacterial survival, then inhibition of iNOS in p38MAPKi and STAT3i senescent cells should rescue this effect on infection." (PMID 34746026, 2021). "Unfortunately, we lack the metadata to see if the differential STAT3 expression could be linked to features like the severity of the infection." (PMID 35173764, 2021). "First, they showed that STAT3 activation was associated with IL-10 production by NK cells during Lm infection by detecting phosphorylated STAT3 (p-STAT3) in the lysates of NK cells purified from Lm-infected B6 mice at both 24 h and 72 h post-infection." (PMID 35053151, 2021). "However, STAT3 deficiency is detrimental for parasite control, prolonging pathology in the first infection." (PMID 32634740, 2020). "We believe IVIG combined with antibiotic therapy may help reduce the opportunity for infection in STAT3-deficient patients." (PMID 32944025, 2020). "For example, strong inhibitors of STAT3 could cause fatigue, diarrhea, infection, and periphery nervous system toxicities." (PMID 32733808, 2020). "We further found that STAT3-deficient macrophages expressed less Arginase-1, and that mice lacking STAT3 in the myeloid compartment (LysMCrexSTAT3fl/fl) were unable to reject a secondary infection with H. polygyrus." (PMID 31708913, 2019). "However, overexpression of PERK caused the increase of cytosolic PERK expression under CA16 infection, phosphorylated STAT3 protein, and promoted NF-κB expression." (PMID 30186868, 2018). "Similarly, the risk of C. difficile infection in humans is higher in LEPR Q223R (rs1137101) model, which is a homozygous allelic mutation that results in impaired STAT3 signaling and increased dissemination of infection." (PMID 29868503, 2018). "Likewise, in rabies virus (RABV) infections, viral protein P associates with p-STAT3 in the cytoplasm, impeding its nuclear translocation." (PMID 29543893, 2018). "Thus, we consider it unlikely that the increase in pulmonary neutrophils observed during infection occurs as a direct consequence of STAT3 deficiency in these cells." (PMID 29338039, 2018). "One possibility is that H. pylori CagA might activate STAT3 phosphorylation in the later stage of infection and cause the rebounded STAT3 phosphorylation." (PMID 24824519, 2014). "Interestingly, the inactivation of STAT5 and activation of NFκB and STAT3 in AEC also promotes milk loss in the mammary glands after infection." (PMID 24308795, 2013). "A STAT3 mutation results in a defective multiple cytokine signal transduction, including interleukin (IL)-6 and IL-22, leading to impaired Th17 function and thus explaining the susceptibility to infections in HIES." (PMID 22085750, 2011). "Finally, the authors examined STAT3 activation, IL-10 production, Lm burden, and inflammatory myeloid cell accumulation in the organs of IL-10Rα deficient-NK cells (NKIl10R−) mice at 72 h post-infection with Lm." (PMID 35053151, 2021). "Moreover, NK cells from NK15Rα− and B6 mice had similar amounts of total STAT3, but the amount of p-STAT3 was significantly reduced in the IL-15Rα-deficient NK cells at 72 h post-infection, which indicated that this receptor contributes to the STAT3 activation." (PMID 35053151, 2021).